CXCR4 (C-X-C motif chemokine receptor 4)
Diseases named in the same sentence as CXCR4 in open-access papers (continued):
Sharing a sentence is not in itself a finding about the gene and the disease.
glioblastoma (continued). "Enhanced SDF-1 and CXCR4 expression was observed not only in low-grade glioma such as oligoastrocytomas and astrogliomas, but also in areas of core necrosis and marginal infiltration of glioblastoma." (PMID 37790751, 2023). "Consequently, the NPs block CXCL12/CXCR4 signaling, leading to the inhibited glioblastoma proliferation and reduced infiltration of CXCR4+ M‐MDSCs into the TME, restoring the integrity of the blood–brain barrier (BBB), and induced ICD." (PMID 36479842, 2023). "More recently, it was found that ERK signal may be involved in the potential contribution of CXCL12/CXCR4 to survival of cancer cells and chemoresistance in glioblastoma." (PMID 38031087, 2023). "In addition, it has been shown that CXCR4 is consistently co-expressed with its ligand CXCL12 in glioblastoma multiforme and that high levels of CXCL12 attract CXCR4-positive vascular and inflammatory cells and promote tumor cytokine secretion." (PMID 37626511, 2023). "In addition, MVIH is involved in the upregulation of AKT and CXCR4 by sponging miR-302a leading to cell proliferation and invasion in glioblastoma." (PMID 36471781, 2022). "In fact, CXCR4 was found highly expressed on metastatic glioblastoma cells relying on VCO." (PMID 36119528, 2022). "Indeed, plerixafor infusion or an administration of an anti-CXCR4 mAb have shown the capability of inhibiting post-irradiation tumor revascularization in mouse and human glioblastoma." (PMID 36568151, 2022). "Furthermore, in glioblastoma the inhibition of CXCR4 and CXCL12 by a miRNA cluster blocked tumor development in mice with cancer cells implanted into the striatum and decreased the expression of OCT4 and NANOG in vitro." (PMID 36118530, 2022). "68Ga-Pentixafor may have a role in selecting patients with glioblastoma who may benefit from therapies targeting CXCR4." (PMID 36140541, 2022). "Plerixafor (AMD3100), a CXCR4 antagonist, was used in combination with chemo-radiotherapy for the treatment of glioblastoma and studied for its ability to prevent the recurrence of glioblastoma after radiation treatment (NCT03746080)." (PMID 35158779, 2022). "There are many other elements of brain tumor biology where CXCR4 is responsible for developing glioblastoma, including cancer-related cells’ ability to resist radiotherapy and chemotherapy, and there are migration and production of the blood supply to the tumor." (PMID 36015199, 2022). "The CXCL12—CXCR4 axis is extensively expressed in the normal brain and plays an important role in CNS development, but its participation in glioblastoma may be an example of tumor cells “hijacking” physiological processes in the CNS." (PMID 35269652, 2022). "The contribution of CXCL12 and its receptor CXCR4 in glioblastoma may be considered as an example of tumor cells “hijacking” of physiological processes in CNS." (PMID 34200145, 2021). "In addition, transfection studies in human glioblastoma cell lines revealed the requirement of NANOG to express CXCR4." (PMID 34638956, 2021). "Double immunostaining of Cx43 and either ACKR3 or CXCR4 in two patient-derived glioblastoma-initiating cell lines with endogenous expression of the three proteins further indicated that a higher fraction of Cx43 is co-localized with ACKR3, in comparison with CXCR4." (PMID 32978390, 2020). "In glioblastoma high levels of CCR5, CXCR4, CXCR7, CCR7, and CCR10 are linked to poor prognosis." (PMID 32545571, 2020). "Upregulated expression of CXCL12 and its receptor CXCR4 was observed in various types of malignant CNS tumors, including low-grade oligodendrogliomas, oligoastrocytomas, and astrogliomas as well as high-grade glioblastomas." (PMID 32456359, 2020). "High levels of CXCR4/CXCL12 expression in glioblastomas and in PCNSL have been shown previously." (PMID 32239371, 2020). "In addition, hypoxia upregulates the expression of SDF-1α and its receptor CXCR4 in glioblastoma tumors and bone marrow via HIF-1α." (PMID 32079173, 2020).
glioblastoma (continued). "Based on these preclinical studies, a clinical phase I/II study was published in 2019, showing that the infusion of the CXCR4 inhibitor plerifaxor was well tolerated as an adjunct to standard chemoirradiation with newly diagnosed glioblastoma and improved local control of tumor recurrences." (PMID 33036204, 2020). "In this communication, we aim to elucidate how disruption of the SDF-1α–CXCR4 interaction using the FDA-approved CXCR4 inhibitor plerixafor (AMD3100) may be used to force slowly-dividing cancer stem cells out of their niches in glioblastoma and AML." (PMID 32079173, 2020). "In fact, it could be shown experimentally that all components of the CXCL12/CXCR4/ACKR3 axis are relevant for recurrence of glioblastoma after radiotherapy, as inhibition of ACKR3 alone in combination with irradiation was also effective in preclinical models." (PMID 30813533, 2019). "In U87MG glioblastoma growth was unaffected by CXCR4 antagonists, AMD3100 and Pep R." (PMID 31661001, 2019). "The CXCL12/CXCR4 axis is a key regulator of the post-radiotherapy microenvironment in glioblastoma." (PMID 30813533, 2019). "In addition, CXCR4 was reported to be upregulated under hypoxic conditions in glioblastoma, via HIF-1α and VEGF." (PMID 31336612, 2019). "With the aim of understanding if CXCL14 functional effects we observed on glioblastoma cell lines may be mediated by CXCR4, we employed the specific CXCR4 inhibitor AMD3100 in proliferation assays of U87MG cells incubated with NIH-CXCL14 conditioned medium." (PMID 31117166, 2019). "There is one study that shows CXCR4‐induced invasion in a 3D setting, increased invasion of glioblastoma spheroids which could be abrogated through proteolytic cleavage of CXCL12 by cathepsin K." (PMID 29959873, 2018). "Moreover, transduction of the YTS NK cell line (containing an EGFR-specific chimeric antigen receptor) with CXCR4 has been shown to enhance infiltration in glioblastoma xenograft models overexpressing CXCL12, resulting in improved survival." (PMID 28923105, 2017). "However, the role of CXCR4 in modulating the stem-like cell properties of rat glioblastoma remains ambiguous." (PMID 23961808, 2013). "In addition, antisense CXCR4 overexpression in glioblastoma cells has been shown to cause the inhibition of cell proliferation, indicating that the SDF-1/CXCR4 system is also involved in cell proliferation in glioblastoma cell lines." (PMID 24137439, 2013). "However, the current study is the first to show that CXCR4 plays a critical role in maintaining the CSC characteristics of rat RG2 glioblastoma." (PMID 23961808, 2013). "Necrotic foci and the pseudopalisading regions are hypoxic and are the main sites of HIF-1α and VEGF expression in glioblastoma, which may result in high expression of CXCR4." (PMID 22539956, 2012). "Furthermore, CXCR4 expression was found upregulated in glioblastoma and its consecutive receptor inhibition was followed by tumour cell arrest." (PMID 16819541, 2006). "Studies in glioblastoma (GBM) suggest an important role of CXCR4 in cell proliferation and in maintaining the neoplastic phenotype of GBM cells." (PMID 37697316, 2023). "The results showed that CXCR4 was highly expressed in GBM and had an independent prognostic value in glioblastoma." (PMID 37626511, 2023). "Additionally, CXCR4 gMFI was significantly increased for all CD8+ T-cell subsets in glioblastoma." (PMID 35464424, 2022). "As high proportions of both blood and glioblastoma-associated CD4+ T-cell subsets expressed CXCR4, the geometric mean fluorescence intensity (gMFI) was compared to determine whether CXCR4 abundance on T-cell subsets differed between glioblastoma and blood samples." (PMID 35464424, 2022). "In addition, CXCR4 expression is regulated by NANOG in glioblastoma cells." (PMID 34638956, 2021). "Moreover, CXCR4 expression requires NANOG in human glioblastoma cells." (PMID 34638956, 2021).
glioblastoma (continued). "The chemokine receptor CXCR4 plays a crucial role in tumors, including glioblastoma multiforme (GBM), the most aggressive glioma." (PMID 28423060, 2017). "Interestingly, in the contralateral hemisphere no vimentin+ cells were detected either after peptide R or Plerixafor treatment, suggesting that both CXCR4 antagonists could abrogate dissemination of glioblastoma cells at distant cerebral sites." (PMID 27015814, 2016). "Here we show the efficacy of the newly synthesized CXCR4 antagonist peptide R in modulating the intrinsic properties of glioblastoma cells and their microenvironment in an experimental model of GBM." (PMID 27015814, 2016). "Likewise, CD133+ glioblastoma cancer stem cells with increased resistance to a range of chemotherapeutic agents, including paclitaxel, express high levels of CXCR4, and high surface expression of this chemokine receptor is considered a marker of cancer stem cells." (PMID 23442791, 2013). "Among these, co-expression patterns involving genes such as CXCR4 and HSPA5 had significant prognostic value in gastric cancer and glioblastoma." (PMID 41948345, 2026). "Recent studies suggest a complex interplay between CXCR4 and S1P1 signaling in conditions such as multiple myeloma, glioblastoma, and neurodegenerative diseases, where CXCR4 is a primary therapeutic target." (PMID 40012038, 2025). "A similar CXCR4 antagonist, PRX177561, in combination with anti-VEGF therapy in glioblastoma, significantly extended the time to progression and disease-free survival in several mouse models." (PMID 38612911, 2024). "Concomitant expression of the CXCR1 or CXCR4 transgene on CAR-NK cells has also demonstrated enhanced migration to CD19+ hematological tumors, glioblastoma and ovarian tumors." (PMID 37563648, 2023). "Likewise, combined immunotherapy with anti-CXCR4 and anti-PD-1 antibodies conferred a noteworthy survival advantage compared to monotherapy treatment, also modulating tumor-infiltrating leukocytes in the glioblastoma microenvironment as evaluated by an in vivo model." (PMID 36980182, 2023). "For example, targeting VEGF via monoclonal antibody combined with CXCR4 antagonist in glioblastoma resulted in enhanced survival, and the use of POL5551 alone as the CXCR4 antagonist affected the existing CSCs." (PMID 37328876, 2023). "Prominin-1, or CD133, is a widely explored CSC biomarker associated with normal neural stem cells, and thus is commonly used in glioblastomas, together with other CSC markers such as CD24, CD44, CXCR4, Oct3/4, and Nanog." (PMID 38139085, 2023). "CXCR4 expression was uniformly high for all CD8+ T-cell subsets and significantly enriched in glioblastoma compared to peripheral blood." (PMID 35464424, 2022). "Analysis of exosomes from glioblastoma cells showed that they are enriched with the proangiogenic factors VEGF, angiogenin, TGFβ, IL-8, IL-6, MMP2, MMP9, TIMP-1, TIMP-2, and CXCR4." (PMID 35740619, 2022). "However, in contrast to enrichment of CXCR4+ T cells in glioblastoma, the greater abundance of CXCR4 on these cells may reflect redundancy of this axis in tumour infiltration as ligation of CXCR4 by CXCL12 results in receptor internalisation and desensitisation." (PMID 35464424, 2022). "With respect to CXCR4-targeted therapies in glioblastoma, the first and most studied CXCR4 antagonist, AMD3100 (Plerixafor), has been reported to inhibit the growth of GBM36 and to reduce glioblastoma stem cell survival in preclinical studies." (PMID 36140541, 2022). "Overall, CCR5 and CXCR4 show the most prominent expression on CD8+ T-cell subsets in glioblastoma tissues, with CCR2, CXCR3 and CXCR6 displaying subset-specific glioblastoma enrichment in Tcm, Tem, and Tcm and Temra populations respectively." (PMID 35464424, 2022).
glioblastoma (continued). "Having identified that CCR2+, CCR5+, CXCR3+, CXCR4+, and CXCR6+ T-cell subsets were enriched in glioblastoma, we subsequently validated the expression of complementary chemokines in dissociated glioblastoma biopsies and patient-derived glioblastoma cell-lines." (PMID 35464424, 2022). "Seven pilot patients with recurrent glioblastoma underwent [68Ga]Ga-Pentixafor PET; residual resected tissue was stained for CXCR4." (PMID 33550492, 2022). "Strikingly, VEGF/VEGFR inhibition elevates CXCL12 and CXCR4 expression in the TME of colorectal cancer (CRC) and glioblastoma, thus bypassing VEGF-dependent angiogenesis blockade and contributing to tumor recurrence." (PMID 36568151, 2022). "In glioblastoma multiforme cells, CXCL12/CXCR4 upregulates FOXM1 expression, promoting tumor migration and invasion." (PMID 36591565, 2022). "Recent studies have shown that chemokines expression of CXCL2, CX3CL1, CCL5, and CCL2 and chemokine receptors CCR5, CX3CR1, CXCR2, CXCR4, CXCR6m and CXCR7 are significantly high in glioblastoma tumors." (PMID 35954362, 2022). "Using synthetic protein nanoparticles (SPNPs)-mediated delivery of CXCR4 antagonist AMD3100 inhibited glioblastoma proliferation by suppressing CXCL2/CXCR4 pathway and reduced the infiltration of CXCR4+ monocytic myeloid-derived suppressor cells (M-MDSCs)." (PMID 36015256, 2022). "The CXCR4/CXCR7/CXCL12 signaling pathway has been extensively studied in recent years and is one of the best-evaluated chemokine signaling pathways in the glioblastoma microenvironment." (PMID 34203660, 2021). "Utilizing CXCR4 and CXCL12 antibodies markedly inhibited glioblastoma cell proliferation and thus tumor growth." (PMID 34203660, 2021). "The CXCR4/CXCR7/CXCL12 signaling pathway plays an important role in proliferation, differentiation, cell survival and chemotaxis in glioblastoma." (PMID 34203660, 2021). "MiR-302-367 cell-to-cell transfer decreases the expression levels of CXCR4/SDF1, SHH, cyclin D, cyclin A, and E2F1 to inhibit glioblastoma growth." (PMID 34113619, 2021). "In the main signaling pathways, Wnt/β-Catenin, TGFβ, PI3K/Akt, ERK, CXCR4, BIRC5, CTNNB1, FZD4, HGF, EGFR, and other proteins enhance the expression of EMT markers and promote the migration and proliferation of glioblastoma." (PMID 32154177, 2020). "Another CXCR4 antagonist, POL5551, exhibits inhibitory effect on glioblastoma growth and dissemination induced by anti-VEGF therapy." (PMID 33363463, 2020). "GSCs and HSCs express the receptor C-X-C receptor type 4 (CXCR4), which binds to the chemoattractant stromal-derived factor-1α (SDF-1α), which is highly expressed in GSC niches in glioblastoma and HSC niches in bone marrow." (PMID 32079173, 2020). "In an NK cell line, even the combination of CAR and CXCR4 were evaluated, showing that YT2 cells expressing EGFRvIII-CAR and CXCR4 migrate to and specifically kill SDF-1-secreting glioblastoma cells." (PMID 32983147, 2020). "A recent study showed that the AhR exhibited tumor suppressor-like activity in established and patient-derived glioblastoma cells and genomic analysis showed that this was due, in part, to suppression of CXCL12, CXCR4 and MMP9." (PMID 32731514, 2020). "AMD3465 reduced the growth of xenografts of glioblastoma multiforme and medulloblastoma cell lines and the CXCR4 antagonist PRX177561, increased the antitumor effects of Bevacizumab and Sunitinib in subcutaneous or orthotopic xenografts of glioblastoma models." (PMID 30894861, 2019). "Since recurrence of glioblastoma after radiotherapy relies on vasculogenesis, targeting CXCL12/CXCR4 was suggested as a novel therapeutic rationale in combination with radiotherapy in these tumors." (PMID 30813533, 2019). "In glioblastoma (GBM), CXCR4 expression is higher in more aggressive tumors and is further upregulated by anti-angiogenic therapies." (PMID 30894861, 2019).
glioblastoma (continued). "Differential activation of SDF-1/CXCR4 signaling, stem cell specific transcriptional factors, PI3K, Akt, and mTOR have been related to glioblastoma progression and aggressiveness." (PMID 31007847, 2019). "A phase I/II study of the CXCR4 antagonist USL311 alone and in combination with Lomustine is ongoing in patients with advanced solid tumors and relapsed/recurrent glioblastoma multiforme (NCT02765165)." (PMID 30894861, 2019). "One driver of glioblastoma dissemination might be hypoxia through HIF-1α mediated up-regulation of SDF-1 and CXCR4 in GBM cells." (PMID 30622535, 2018). "In glioblastoma, CXCL12 stimulation of CXCR4 increased cell cycle progression and EMT through expression of survivin." (PMID 29959873, 2018). "We used immunofluorescence staining to quantify expression of CXCR4 and CXCL12 in tissue samples from patients diagnosed with glioblastoma, with one cohort comprising samples taken prior to therapy and one with samples taken after therapy." (PMID 30451884, 2018). "Like CXCR4, ACKR3 has been considered a potential target for therapy of a number of cancers, including glioblastoma, endometrial carcinoma, and lung cancer." (PMID 29088715, 2017). "In glioblastoma, a portion of the tumor vasculature arises from CSCs which have been reported to differentiate to tumor vessel pericytes upon CXCL12/CXCR4 and TGFβ signaling." (PMID 29112161, 2017). "Collectively from all these results, we conclude that epigenetic silencing of GNG4 in glioblastoma, specifically the mesenchymal subtype, is essential because its expression would inhibit GBM cell migration mainly through inhibition of ERK pathway downstream to SDF1α/CXCR4-dependent signaling." (PMID 27382437, 2016). "Here, we quantified fractionated IR-induced migration/brain infiltration of human glioblastoma cells in vitro and in an orthotopic mouse model and analyzed the role of SDF-1/CXCR4 signaling and BK channels." (PMID 26893360, 2016). "As previously shown in glioblastoma cells, hypoxia and HIF-1α can regulate the expression of CXCR4 in colon cancer cell lines." (PMID 24629239, 2014). "Three human genes, CD74, CXCR4, and VIM, were common to both the glioblastoma and lymphoma transplants." (PMID 25259521, 2014). "In this study, we investigated the roles of CXCR4 and CXCR7 in glioblastoma using primary patient-derived GBM cells." (PMID 23555768, 2013). "The chemokine receptor CXCR4 is crucial for maintaining the self-renewal, proliferation, therapeutic resistance, and angiogenesis of GSCs of rat RG2 glioblastoma." (PMID 23961808, 2013). "By using rat RG2 glioblastoma, we showed that disrupting the CXCL12/CXCR4 axis impairs the characteristics of GSCs." (PMID 23961808, 2013). "U373-MAGI-CXCR4CEM cells are human glioblastoma cells that have been transduced to constitutively express CD4 and CXCR4." (PMID 24156270, 2013). "We previously demonstrated that systemic administration of the specific CXCR4 antagonist AMD 3100, inhibited the intracranial growth of U87 glioblastoma xenografts by increasing apoptosis and decreasing proliferation of tumor cells." (PMID 22427929, 2012). "Moreover, activation of the CXCL12/CXCR4 signalling pathway reportedly increases MMP-9 and VEGF expression in glioblastoma." (PMID 38594611, 2024). "For instance, SDF-1/CXCR4 modulates epithelial-mesenchymal transformation (EMT) of sacral chondrosarcoma, glioblastoma, and oral squamous cell carcinoma SDF-1/CXCR-4 signal transduction also regulates actin polymerization, vascular endothelial cell adhesion and migration to BM-MSCs." (PMID 39081954, 2024). "The CXCR4 antagonist AMD3100 had the capacity to increase the effect of Vatalanib, a vascular endothelial growth factor (VEGF) R2 tyrosine kinase inhibitor, counteracting the growth and cell migration in an in vivo model of glioblastoma." (PMID 36980182, 2023). "Inhibition of both CXCR4 and SDF-1α can disrupt the niche of cancer stem cells in glioblastoma." (PMID 37560473, 2023).